TRPV4 (transient receptor potential cation channel subfamily V member 4)
Diseases named in the same sentence as TRPV4 in open-access papers (continued):
Sharing a sentence is not in itself a finding about the gene and the disease.
lung carcinoma (7 papers, 2019 to 2025). "Previous research has shown that the loss of endothelial TRPV4 promotes lung cancer, and TRPV4 activation inhibits proliferation." (PMID 39744893, 2025). "Currently, only a few channels of the TRP family have been characterized as having a role in tumor angiogenesis, such as TRPV4, TRPV3, TRPM3, and TRPA1, demonstrated in lung carcinoma, renal cell carcinoma, cancer-associated fibroblast, and prostate cancers." (PMID 37576552, 2023). "TRPV4 overexpression in human lung cancer cell lines induces cell death and inhibits cell proliferation and migration." (PMID 37892239, 2023). "The results demonstrated that low levels of TRPV4 were detected in clinical lung carcinoma specimens." (PMID 34669779, 2021). "We have previously demonstrated that conditioned media (TCM) from human lung cancer cells transformed normal human endothelial cells into a tumor endothelial cell-like (TEC) phenotype via downregulation of TRPV4 channels." (PMID 35004649, 2021). "The levels of TRPV4 were detected in human lung cancer tissues and the paired paracarcinoma tissues by real-time PCR and western blotting analysis." (PMID 34669779, 2021). "In a lung cancer model, TRPV4 activation normalizes tumor vasculature and promotes the effectiveness of chemotherapy." (PMID 33322037, 2020). "The latest findings indicate that TRPV4 induces apoptosis via p38 MAPK in human lung cancer cells." (PMID 37892239, 2023). "Collectively, this can imply that TRPV4 is a candidate target for human lung cancer therapy." (PMID 37892239, 2023). "Here, we elucidated the effects of TRPV4 and molecular mechanisms in human lung cancer cells." (PMID 34669779, 2021). "Collectively, our findings indicated that TRPV4 induced apoptosis via p38 MAPK in human lung cancer cells and suggested that TRPV4 was a potential target for therapy of human lung cancers." (PMID 34669779, 2021).
overactive bladder (7 papers, 2017 to 2025). Symptom of overactive detrusor muscle of the urinary bladder that contracts with abnormally high frequency and urgency. "The overactivation of TRPV4 was associated with bladder overactivity and increased urinary frequency." (PMID 39334811, 2024). "Of pathological significance, this study also provides the first evidence for TRPV4 involvement in aging, oxidative stress, and overactive bladders." (PMID 31914645, 2020). "TRPV4 antagonists decrease bladder activity making it a promising target for overactive bladder and other bladder disorders." (PMID 29321730, 2017). "In addition, the TRPV4 agonist, GSK1016790A, was examined for its potential to improve underactive bladders, and TRPV4 antagonists were evaluated for their ability to ameliorate overactive bladders." (PMID 37569884, 2023). "TRPA1 up-regulation and TRPV1/TRPV4 down-regulation may account for the MGO-induced bladder overactivity." (PMID 32317986, 2020). "Overactive bladders exhibited greater TRPV4‐induced ATP release with age dependence." (PMID 31914645, 2020). "Notably, TRPV4 antagonists have shown effectiveness in alleviating stress-induced bladder issues by improving bladder capacity and reducing urinary frequency, suggesting that TRPV4 is a potential therapeutic target for treating bladder disorders, including overactive bladder." (PMID 39334811, 2024).
ulcerative colitis (7 papers, 2018 to 2025). An inflammatory bowel disease involving the mucosal surface of the large intestine and rectum. "TRPV4 mRNA expression is increased in IBD patients, and selective blockade of TRPV4 in a mouse model of ulcerative colitis reduced intestinal inflammation and relieved pain." (PMID 39596193, 2024). "The aim of this study was to evaluate the expression levels of TRPV1, TRPV2, TRPV3 and TRPV4 in mucosa epithelial cells of colonic biopsies from patients with ulcerative colitis (UC) in comparison to colonic resections from non-IBD patients (control group)." (PMID 29914124, 2018).
bladder cancer (6 papers, 2017 to 2025). "In bladder cancer, the inhibition of overexpressed TRPV4 significantly reduced E-cadherin expression." (PMID 36830651, 2023). "Recent reports show a decreased of TRPV4 expression in skin and bladder cancers, bladder and liver, and an overexpression in cervix, bladder, colon, lung, and uterus cancers, and TRPV4 is also involved in tumor cells angiogenesis." (PMID 32186440, 2020). "In comparison to para-carcinoma tissues, TRPV4 was highly expressed in bladder cancer tissues." (PMID 36830651, 2023). "In models investigating bladder cancer tissue and para-carcinoma tissue, the variations in TRPV4 expression were not evident, but TRPV4 was able to detect mechanical and chemical stimuli, induce calcium influx, and promote ATP release." (PMID 38730655, 2024). "The changes in TRPV4 expression in bladder cancer tissue and para-carcinoma tissue were not very clear; however, TRPV4 definitely detected mechanical and chemical stimuli, induced calcium influx, and promoted ATP release." (PMID 36830651, 2023). "Thus, our findings indicate that bladder cancer does not affect global TRPV4-dependent [Ca2+]i increase in DSM cells, but essentially reduces Vm depolarization associated with TRPV4 activation." (PMID 33184390, 2020).
brain infarction (6 papers, 2015 to 2025). Tissue necrosis in any area of the brain, including the cerebral hemispheres, the cerebellum, and the brain stem. "In contrast, blocking TRPV4 activation attenuated brain infarction after occlusion and reperfusion of the middle cerebral artery." (PMID 35323756, 2022). "Intracerebroventricular injection of HC-067047, a specific TRPV4 antagonist, reduced brain infarction 24 h after tMCAO." (PMID 32974355, 2020). "ICV injection of the TRPV4 antagonist HC-067047 reduced brain infarction after reperfusion for 48 h in mice with middle cerebral artery occlusion (MCAO)." (PMID 26043075, 2015). "The TRPV4 antagonist GSK2193874 or EA‐mediated TRPV4 suppression reduces cerebral infarction and neurological dysfunction in the MCAO/R model by suppressing the activation and proinflammatory polarization of microglia and the mRNA levels of Tnf‐α, Il‐6, and ccl2." (PMID 41399206, 2025). "Inhibition of TRPV4 reduces neurological injury after cerebral infarction, and leads to apoptosis of mouse retinal ganglion cells, which may contribute to the activation of Ca2+-dependent signaling pathways." (PMID 29238305, 2017). "In our previous study, brain infarction at 24 h post MCAO is reduced by TRPV4 antagonist HC-067047." (PMID 26043075, 2015).
cyst (6 papers, 2013 to 2025). A sac-like closed membranous structure that may be empty or contain fluid or amorphous material. "Polycystic kidney disease (PKD) manifests as progressive cyst growth due to cAMP‐dependent fluid secretion along with deficient mechanosensitivity and impaired TRPV4 activity." (PMID 36946001, 2023). "TRPV4 activity was significantly impaired in isolated murine collecting duct (CD)-derived cyst monolayers, with abnormal subcellular localization of the channel leading to decreased basal Ca+2 levels and loss of flow-mediated Ca+2 signaling." (PMID 40136708, 2025). "This strongly implies that TRPV4 activity specifically in cyst cells is a critical factor which determines the rate of cystogenesis." (PMID 36946001, 2023). "Here, we boost this argument by demonstrating that physiologically relevant stimulation of TRPV4 activity with high KCl diet is an effective tool to counteract cyst formation." (PMID 36946001, 2023). "In this study it was also shown that the systemic pharmacological activation of TRPV4 for long periods of time progressively reinstated the mechanosensitivity of cyst cells and diminished the progression of ARPKD in the rat model." (PMID 32481620, 2020). "Treatment with GSK1016790A, a selective TRPV4 activator, inhibited cyst growth in PCK rats." (PMID 37024297, 2023). "TRPV4 activity is drastically impaired in cyst cells of ARPKD and ADPKD." (PMID 36946001, 2023). "Loss of TRPV4, however, did not result in cyst formation, which suggests that mechanosensitive activation of this channel complex alone is not sufficient for cyst formation." (PMID 23076254, 2013). "Understanding the molecular mechanisms underlying these dysfunctions has opened the door for innovative therapeutic strategies, including TRPV4 activators, CFTR inhibitors, and calcimimetics, to mitigate cyst growth and preserve renal function." (PMID 40136708, 2025). "Activation of TRPV4 by 4αPDD and GSK1016790 raises the intracellular Ca+2 levels, which leads to the inhibition of cholangiocyte proliferation in vitro and a reduction in cyst growth in vivo, mediated by the Akt and B-RAF/ERK1/2 signaling pathways." (PMID 40136708, 2025). "While TRPV4 is a crucial element of ciliary mechanosensitivity in MDCK cells in vitro, it does not have a significant role in cyst formation in TRPV4-deficient mice or zebrafish." (PMID 40136708, 2025). "In contrast, knockdown of PC2 abolished normal cyst formation in the zebrafish pronephros, but knockdown of TRPV4 did not disturb the cyst formation." (PMID 37780208, 2023). "In 2010, it was shown that the expression of TRPV4 in PCK cholangiocytes is increased and that activation of the channel in these cells not only inhibited cell proliferation by 25%–50% and cyst growth by 3-fold in cultures, but also decreased the cystic area in in vivo experiments." (PMID 32481620, 2020).
cystic fibrosis (6 papers, 2008 to 2024). Autosomal recessive disorder caused by pathogenic variants in the CFTR gene (cystic fibrosis transmembrane conductance regulator), which encodes a chloride and bicarbonate channel expressed in epithelial cells, and follow the diagnosis criteria. "Understanding the signaling mechanisms that govern TRPV4 function is vital, as it holds potential as a therapeutic target for respiratory diseases, including cystic fibrosis, the most prevalent muco-obstructive disease." (PMID 39408877, 2024). "As mentioned in Section 4, both CFTR and TRPV4 play important roles in cystic fibrosis." (PMID 32481620, 2020). "It has also been demonstrated that, in vitro and in vivo, TRPV4 is constitutively a part of the signaling pathways of cytosolic phospholipase A2 (cPLA2α), MAP-kinases, and NF-κB, supporting its involvement in the inflammatory response and potentially in cystic fibrosis pathogenesis." (PMID 32481620, 2020).
diabetic neuropathy (6 papers, 2007 to 2025). A chronic, pathological complication associated with diabetes mellitus, where nerve damages are incurred due to diabetic microvascular injury involving small blood vessels that supply these nerves, resulting in peripheral and/or autonomic nerve dysfunction. "The upregulation of TRPV4/Piezo1 transcription by TGFβ2 predicts exaggerated responsiveness to mechanical loading, as reported for chemotherapy, neuropathic pain, cancer, and diabetic neuropathy." (PMID 39574569, 2025). "Moreover, a different research group showed that TRPV4 expression was increased 2 weeks post-induction of the painful diabetic neuropathy model in rats." (PMID 36670886, 2022). "Moreover, another neuropathic pain rodent model that evaluated the TRPV4 channel role is painful diabetic neuropathy." (PMID 36670886, 2022). "The physiopathology of diabetic neuropathy involves hyperglycemia, oxidative stress, and mitochondrial dysfunction, which could generate TRPV4 activation." (PMID 36670886, 2022). "The upregulation of TRPV4/PIEZO1 transcription by TGFβ2 predicts exaggerated responsiveness of the outflow pathway to mechanical loading, as reported for TRPV4-dependent mechanical hyperalgesia in chemotherapy, neuropathic pain, cancer, and diabetic neuropathy." (PMID 40552711, 2025). "We used immunohistochemistry associated with a battery of antibodies to identify the axon and Schwann related cells (since both are involved in diabetic neuropathy) and a series of putative mechanoproteins (PIEZO2, ASIC2 and TRPV4) which are involved in mechanotransduction." (PMID 34640627, 2021).
Dry skin (6 papers, 2021 to 2024). Skin characterized by the lack of natural or normal moisture. "For example, a potential trial could be topical application of the TRPV4 selective inhibitor for treating chronic itch, based on recent exciting findings about keratinocyte TRPV4 in cholestatic itch and dry-skin-associated itch." (PMID 34299208, 2021). "It has been recently reported that TRPV4 contributes to dry skin-induced pruritis, mediated by serotonin receptors." (PMID 34925342, 2021). "Our results revealed that the mRNA expression levels of Trpa1 (t8 = 4.798, P = 0.0014), Trpv1 (t8 = 3.258, P = 0.0116), and Trpv4 (t8 = 4.297, P = 0.0026) significantly increased in the DRGs of dry skin-induced chronic itch model." (PMID 35095413, 2021). "Moreover, TRPV4‐expressing macrophages and keratinocytes contribute differentially to squaric acid dibutylester (SADBE)‐induced allergic and dry skin‐associated non‐allergic chronic itch." (PMID 38957035, 2024). "Previous studies have demonstrated that protease-activated receptor 2 (PAR2), TRPV3, and TRPV4, are involved in the production of TSLP in keratinocytes under dry skin conditions." (PMID 34925342, 2021).
Hyperglycemia (6 papers, 2015 to 2021). An increased concentration of glucose in the blood. "Since hyperglycemia downregulates TRPV4 in the ECs of the retinal microvasculature, we investigated TRPV4 expression by immunohistochemistry (IHC) in 9 dpf zebrafish larvae exposed to glucose or mannitol with or without SNP treatment." (PMID 31481433, 2019). "In the current paper, we demonstrate that TRPV4 is functionally expressed in the endothelium of the retinal microcirculation and that both channel expression and activity is downregulated by hyperglycaemia." (PMID 26047504, 2015). "Similarly, in db/db and STZ -induced diabetic C57BLKS/J mice, mRNA and protein levels of TRPV4 were significantly decreased in aortas, indicating that hyperglycemia is a crucial factor for the diminished TRPV4 expression, and impairs the endothelium-dependent vasodilation observed in diabetic mice." (PMID 33716794, 2021). "The 4-week streptozotocin treatment did not alter the body weight of wt and Trpv4-/- mice (19.4 ± 0.4 g; n = 11 vs. 18.3 ± 0.5 g; n = 9; P > 0.05), but it induced hyperglycemia at similar levels (P > 0.05) in both groups (412.5 ± 22.9 mg/dl; n = 11 vs. 499.7 ± 4.7 mg/dl; n = 9, S1 Fig)." (PMID 31048895, 2019).
Insulin resistance (6 papers, 2017 to 2024). Increased resistance towards insulin, that is, diminished effectiveness of insulin in reducing blood glucose levels. "In adipocytes, TRPV4 knockout mice were protected from hypertrophy and insulin resistance, suggesting that TRPV4 plays an important role in promoting adipocyte hypertrophy." (PMID 33021706, 2020).
metatropic dysplasia (6 papers, 2011 to 2025). Metatropic dysplasia (MTD) is a rare spondyloepimetaphyseal dysplasia characterized by a long trunk and short limbs in infancy followed by severe and progressive kyphoscoliosis causing a reversal in proportions during childhood (short trunk and long limbs) and a final short stature in adulthood. "Metatropic dysplasia (MD), is a rare skeletal dysplasia occurring predominantly in infants characterized by a distinctive long torso and short limbs; it is as a result of mutations in the TRPV4 gene." (PMID 31808622, 2019).
ovarian carcinoma (6 papers, 2016 to 2026). A malignant neoplasm originating from the surface ovarian epithelium. "TRPV4 is highly expressed in ovarian cancer and is associated with poor prognosis, specifically worse overall survival (OS), disease-specific survival (DSS), disease-free interval (DFI), and PFS in ovarian cancer." (PMID 41465326, 2025). "Furthermore, in patients with colon adenocarcinoma (COAD) or ovarian cancer, high TRPV4 expression was associated with worse overall survival (OS), disease-specific survival (DSS), disease-free interval (DFI), and progression-free interval (PFI)." (PMID 34262942, 2021). "For example, TrpV4, TrpC7, and several TrpM family members (TrpM2, TrpM4, TrpM8) are upregulated in ovarian cancer, where their expression negatively correlates with patient prognosis." (PMID 41557739, 2026). "According to an analysis of The Cancer Genome Atlas and Genotype-Tissue Expression databases, strong TRPV4 expression predicts multidrug resistance and resultant adverse outcomes in ovarian carcinoma." (PMID 37240443, 2023). "Results from the univariate Cox regression analysis suggested that TRPV4 was a risk factor for OS in LGG, ovarian cancer, PAAD, THYM, and UVM patients, while it was a protective factor in CESC, KICH, KIRC, and KIRP." (PMID 34262942, 2021). "In COAD and ovarian cancer, TRPV4 was over-expressed; moreover, high expression levels of TRPV4 predicted worse OS in tumor patients." (PMID 34262942, 2021). "For DSS, TRPV4 was a risk factor in COAD, GBM, LGG, LUSC, ovarian cancer, PAAD, THYM, and UVM and a protective factor in CESC, KICH, KIRC, KIRP, and LUSC." (PMID 34262942, 2021). "TRPV4 mRNA levels in breast, gastric and ovarian cancers correlated with poor clinical outcomes, suggesting a wide role of TRPV4 in human epithelial cancers." (PMID 27291497, 2016). "The oncogenic pathway of TRPV4 in ovarian cancer may be related to fatty acid synthesis, through the calcium-mTOR/SREBP1 signaling pathway, thereby promoting ovarian cancer progression." (PMID 41465326, 2025). "TRPV4 is therefore a potential therapeutic target for ovarian cancer." (PMID 41465326, 2025). "This further verified the great potential of TRPV4 in ovarian cancer." (PMID 35813831, 2022). "It has been reported that TRPV4 promotes the progression of COAD, while no reports on TRPV4 in ovarian cancer are available." (PMID 34262942, 2021).
rosacea (6 papers, 2018 to 2026). A chronic erythematous skin disorder that affects the face. "This evidence illustrates that MC activation stimulated by NPs or TRPV4 promotes neurogenetic inflammation associated with rosacea." (PMID 32047752, 2019). "Finally, TRPV4 expression has also been linked to rosacea, a chronic inflammatory skin disease where some patients experiment an itchy sensation." (PMID 32481620, 2020). "Previous research reported that TRPV4 plays a key role in cathelicidin‐driven mast cell activation in rosacea inflammation." (PMID 38957035, 2024). "LL-37 directly enhanced TRPV expression in huMCs, and TRPV4 expression is essential for the full degranulation of MCs in rosacea." (PMID 32047752, 2019). "Furthermore, the upregulation of TRPV4 expression has been determined in the skin of a murine-rosacea model." (PMID 32481620, 2020). "Interestingly, a recent study in rosacea patients suggested pathological relevant roles of TRPV4 in this skin disease, although activation of TRPV4 in mast cells was shown to be the main driver here." (PMID 29293584, 2018). "Moreover, TRPV4 upregulation is dependent on MRGPRX2 in rosacea." (PMID 32047752, 2019).
acute respiratory distress syndrome (5 papers, 2017 to 2023). Progressive and life-threatening pulmonary distress in the absence of an underlying pulmonary condition, usually following major trauma or surgery. "Inhibition of TRPV4 has also been suggested to be a promising therapeutic route for treating acute lung injury/acute respiratory distress syndrome (ARDS), and more recently for treating COVID-19 patients with lung edema." (PMID 38273937, 2023). "In the current review, we discuss the importance of TRPV4 in macrophages and its role in phagocytosis and cytokine secretion in acute lung injury/acute respiratory distress syndrome (ARDS)." (PMID 32676078, 2020).